SOX4 (SRY-box transcription factor 4)
Diseases named in the same sentence as SOX4 in open-access papers (continued):
Sharing a sentence is not in itself a finding about the gene and the disease.
tumor (continued). "One cluster (C2 Tumor cells) expressed stem-related genes (SOX4 and CD164); the other (C3-Tumor cells) expressed proliferative genes (MKI67 and MCM2)." (PMID 36788228, 2023). "The C2-tumor cluster had high autophagy (ATG5, MAP1LC3B), high plasticity (SOX4, CD164) and low mTORC1 activity (RPS6, MLST8), characteristics of early paligenosis (stages 1-2)." (PMID 36788228, 2023). "Altogether, this study emphasizes the critical roles of SOX4 in the diagnosis and prognosis of tumors, especially in LIHC, and as a promising therapeutic target for tumor treatment." (PMID 37958409, 2023). "By performing the reverted assays, we also found that miR-873-5p functioned as an tumor inhibitor and a DDP sensitizer in ESCC cells via downregulating SOX4." (PMID 35241028, 2022). "On the basis of the CellMarker dataset and our previous studies, tumor cells (marked by EPCAM and SOX4) were isolated from other cell populations through dimensionality reduction and unsupervised clustering analysis." (PMID 35505963, 2022). "Accordingly, we detected and observed an obvious upregulation of E2F7 in both HCC tumor tissues and cells, positively correlated with SP1, SOX4, and Anillin." (PMID 35924788, 2022). "In accord with the findings in vitro, the staining frequency and intensity of BCL9L, SOX4 and AKT1 decreased significantly in downregulated‐NAT10 xenograft tumours." (PMID 35522942, 2022). "Currently, it is documented that SOX4 regulated the invasion, migration, and epithelial–mesenchymal transition (EMT) process of tumor cells through the Wnt/β-catenin pathway." (PMID 35442158, 2022). "Expectedly, HSPA4 overexpression increased the levels of HSPA4, HSPA5, CHOP, SDC-1, SDCBP-1, SOX4, FZD4, and β-catenin in tumor tissues, but 4-PBA inhibited the generation of these proteins." (PMID 35442158, 2022). "Overexpression of FN1, SOX4 and ETV5 were found in 43 paired samples between paracancerous tissues and tumor tissues of HNSCC." (PMID 36212151, 2022). "FN1, SOX4 and ETV5 were further validated in HNSCC patients’ tumor tissues with irradiated failures, which is novel radioresistance biomarkers in HNSCC." (PMID 36212151, 2022). "We and others have recently demonstrated that CUL4B regulates the expression of several tumor suppressors, including MYCN, PIK3CA, HER2, SOX4, C-MYC and CDH2 at the posttranscriptional level." (PMID 35784474, 2022). "In the present study, we identified that hsa_circ_0000277 functioned as a tumor promoter to accelerate the biological development of ESCC and DDP resistance by depending on the miR-873-5p/SOX4/Wnt/β-catenin signaling pathway." (PMID 35241028, 2022). "A prominent example is the SOX4–Axin2 network and the CDX2–Axin2 network, both of which are reported to inhibit the proliferation and tumor formation of cancer cells by suppressing Wnt/β-catenin signaling." (PMID 35625787, 2022). "SOX4 has a central role in promoting EMT, tumor growth and metastasis by directly regulating the expression of many genes involved in tumorigenesis, EMT, metastasis and cancer stemness." (PMID 34055896, 2021). "The positive expression rate of SOX4 and Slug in LSCC was related to pathological differentiation, lymphatic invasion, and pathological tumor node metastasis." (PMID 34283055, 2021). "As part of HIF-1α/CASC15/SOX4/β-catenin axis, CASC15 plays an essential role in cell proliferation, invasion, and tumor development in NSCLC." (PMID 34745939, 2021). "In contrast, the mice transplanted with SOX4KO organoids exhibited a substantially lower tumor outgrowth (3/6 for SOX4 KO1 and 1/6 for SOX4 KO2)." (PMID 34584219, 2021). "In CRC, Previous studies have indicated that METTL14 suppressed the tumor progression by regulating miR-375, lncRNA XIST and SOX4, respectively." (PMID 34916487, 2021). "Together, these data suggest that SOX4 and SOX2 play distinct roles in tumor initiation and progression." (PMID 32427884, 2020).
tumor (continued). "In turn, miR-1193 negatively regulates the expression of SOX4, a transcription factor, belonging to the SOX family, involved in tumor progression and invasiveness." (PMID 32911687, 2020). "SOX4 has been characterized as a master regulator of EMT, notably by upregulating SOX2, a well-known mediator of tumour initiation and cancer stem cell maintenance." (PMID 32586280, 2020). "For instance, miR-370 and miR-132 suppress EMT-related processes inhibiting tumor growth and metastasis via targeting fork head box protein M1 (FOXM1) and SRY-box 4 (SOX4), respectively." (PMID 32391253, 2020). "Wnt synthesis inhibitors blocked the tumor growth with concurrent overexpression of CUL4B and SOX4 in vivo." (PMID 30872583, 2019). "Therefore, the observed phenotype of delayed hair regrowth and wound healing, and high resistance to tumor formation could not be definitively attributed to epidermal deficiency of Sox4, leaving the role of Sox4 in skin unresolved." (PMID 31492871, 2019). "The forces driving Sc/NE‐like and GU tumours into one consensus cluster are most likely a high proliferation rate and frequent E2F3, CDKAL1 and SOX4 genomic amplification at 6p22, which are characteristic of both subtypes." (PMID 28195647, 2017). "What is more, 10, 1 × 102, 1 × 103, 1 × 104 and 1 × 105LncSox4-silenced and Sox4 rescued cells were subcutaneously injected into BALB/c nude mice and tumour initiation was examined 3 months later." (PMID 27553854, 2016). "Thus, SOX4 might exert different effects depending on tumor cell types and context." (PMID 26555193, 2015). "In EAC dataset (GSE13937), we found that SOX4 (P value = 0.003) and HDAC3 (P value = 0.042) were increased in tumor samples compared to adjacent normal tissues." (PMID 25644061, 2015). "Sox4 also plays a central role in the epithelial-mesenchymal transition (EMT) and in primary tumor growth and metastasis." (PMID 25970172, 2015). "Tumor metastasis often leads to poor prognosis of NPC, we then investigated the role of SOX4 in NPC metastasis." (PMID 26578818, 2015). "Inversely, in non-invasive tumor cells miR-31 targets SOX4, EZH2 and HDAC3 by direct and indirect means to inhibit tumor cell invasion." (PMID 25644061, 2015). "Intriguingly, SOX4 can interact with TGF-β, Wnt, Notch and PI3K signaling pathways and activates β-catenin to promote tumor proliferation." (PMID 23251334, 2012). "We noticed that VEGFA, HIF1A, SOX4, SOX9, MMP2, TGFB1 genes are overexpressed together with S6K1 in all 4 tumour types investigated." (PMID 22570651, 2012). "Our work provides initial evidence for human-enriched UBC states and suggests that SOX4 and SOX11 may drive neurogenesis in UBC and gene expression in a subset of Group 4 MB tumour cells." (PMID 41998565, 2026). "Stemness-related genes SOX4 and NFIA exhibited expression in both, mouse xenograft and hGliCS, with SOX11 showing high expression exclusively in hGliCS, compared to monocultured S24 tumor cells." (PMID 40188875, 2026). "Data analysis showed that the expression of SRM and CPA4 mRNAs in tumor tissue increased compared to the adjacent normal tissue, while the expression of SOX4 mRNA did not change." (PMID 39028420, 2024). "Furthermore, SOX4 promotes TMZ resistance in GBM by interacting with EZH2 and coactivating METTL3, resulting in transcriptional plasticity of tumor cells." (PMID 38331879, 2024). "XRCC1 (AUC=0.847), SOX4 (AUC=0.985), and HOXD9 (AUC=0.767) indicated that these three genes could be ideal biomarkers to distinguish LGG from non-tumor tissues." (PMID 38217545, 2024). "SOX4, a member of the SRY-related high mobility group (HMG) box transcription factor (TF) family, has been well-reported to function as a pluripotent and stemness-related TF, regulating embryogenesis and tumor progression in multiple cancers." (PMID 39014441, 2024). "This interaction between SOX4 and BMI1 contributes to tumor growth and metastasis." (PMID 39349443, 2024).
tumor (continued). "Therefore, ADAMTS16 forms a positive feedback loop with the TGF-β1/SOX4 axis to regulate EMT and metastasis, and disruption of this feedback loop inhibits tumor progression." (PMID 39551781, 2024). "Tumor cells promote CAF generation, and the CAFs, in turn, improve the invasiveness and metastasis of the malignant T cells through the IL-6/JAK2/STAT3/SOX4 or IL-6/HIF-1α/SOX4 pathway." (PMID 39963655, 2024). "The correlations between SOX4 expression and the immune infiltrating cells (including CD8+ T cells, CD4+ T cells, B cells, neutrophils, macrophages, and myeloid dendritic cells) across various tumor types were visualized using cluster heatmaps." (PMID 37958409, 2023). "In addition, as a downstream gene of SOX4, DHX9 activates the Wnt/β-catenin signaling pathway then promotes tumor metastasis and drug resistance." (PMID 37214432, 2023). "However, only levels of SOX4 and DUSP4 were reduced after PD1-blockade, where there is expected reactivation of tumor-targeting clones and reduction in the exhaustion phenotype." (PMID 36973261, 2023). "Again, transfection with miR-637 inhibitor failed to increase the number of tumor spheres and up-regulate the expression of stemness-related genes (SOX4, SOX9, Nanog, CD44 and ABCG2) after stable knockdown of WASH in KYSE70 cells." (PMID 36329557, 2022). "In addition, HSPA4 overexpression activated ER stress and Syntenin/SOX4/Wnt/β-catenin pathway in TNBC cells, and also stimulated TNBC tumor growth in 4-PBA-treated mice." (PMID 35442158, 2022). "Interestingly, in our previous study, the Anillin mRNA level showed a swift change when we depleted SOX4 in HCC cells, and the tumor growth was impaired as a result." (PMID 35924788, 2022). "We suppose that SOX4 and Anillin play positive roles in HCC tumor growth synergistically." (PMID 35924788, 2022). "Moreover, overexpression of SOX4 in melanoma leads to phosphorylation of AKT and activation of downstream HIF-1α and c-Myc to promote glycolysis in tumor cells." (PMID 36620597, 2022). "Finally, knockdown of Sox4 suppressed OSCC growth in vivo, and antagonized the acceleration of IL-6 on tumor growth." (PMID 35513871, 2022). "Meanwhile, SOX4 promotes OXPHOS by increasing the expression of MITF, which is not always antagonistic to glycolysis, allowing for a more flexible metabolism of tumor cells." (PMID 36620597, 2022). "As a result, several hub DEFs with maximum intramodular connectivity were identified (e.g., SOX4, EGR1, LEF1, FOS, MITF, KLF4, TCF7, and KDM6B), which might involve CD248-mediated tumor-promoting regulation in CAFs." (PMID 34970489, 2021). "Notably, SOX4 and ETS1, which were identified as activated transcription factors in ECs in the tumor core, were also upregulated in ECs in the tumor core." (PMID 34228647, 2021). "In addition, nude mice experiments revealed that the tumor volume and mass of nude mice declined after injection of sh-MIR4435-2HG, and qRT-PCR indicated that miR-138-5p elevated and Sox4 declined after injection of sh-MIR4435-2HG." (PMID 34532282, 2021). "Then we isolated tumor tissues to assess the level of PITPNA-AS1, SOX4 and miR-92a-3p." (PMID 34496348, 2021). "SOX4 and SOX11, markers of neurogenic RPCs, were also expressed in most tumor cone clusters." (PMID 34003213, 2021). "Importantly, several studies have provided evidence that SOX4 expression was increased in NSCLC and promoted the tumor growth and migration of NSCLC." (PMID 34413915, 2021). "While previous studies have reported that SOX4 can directly modulate tumor cell transcription, our study has demonstrated for the first time that SOX4 can impact tumorigenesis in a non-cell-autonomous fashion." (PMID 30507376, 2018).
tumor (continued). "Based on our current data however we cannot determine the degree to which tumor angiogenesis contributes to the pro-metastatic effects of SOX4, since it is not possible to exclude other processes such as EMT and invasiveness." (PMID 30507376, 2018). "Based on that, SOX4, E2F3 or 6q22.3 amplifications might represent potential targets in this tumor type." (PMID 30072631, 2018). "SOX4 activation promotes ET-1 expression and controls the angiogenic behavior of endothelial cells both in vitro and in vivo, thus affecting tumor-progression in a non-cell autonomous manner." (PMID 30507376, 2018). "Despite observations of increased SOX4 expression in a wide variety of tumors, effects can differ greatly between cancer-types resulting in cellular transformation, increased proliferation, EMT and metastasis, or even tumor-suppression." (PMID 30507376, 2018). "Further, our results demonstrated that ALK signaling involves the activities of N-myc, Sox4, Sta3, and Akt, which together promote increases in tumor neovascularization under non-hypoxic conditions and cell proliferation." (PMID 28837676, 2017). "We then enriched liver TICs by flow cytometer using anti-CD133 antibody, and silenced Stat3 or Sox4 in liver TICs and non-TICs using pSiCoR lentivirus, followed by sphere formation and tumour initiation assays." (PMID 27553854, 2016). "In wild-type (WT) cells, LncSox4 overexpression significantly promoted tumour initiation, while LncSox4 overexpression failed to promote tumour formation in Sox4 knockout cells, validating the critical role of Sox4 in LncSox4-mediated liver TIC activation." (PMID 27553854, 2016). "Immunostaining patterns were heterogenous, with predominantly nuclear and/or cytoplasmic immunostained SOX4 protein in tumor cells, but with weak or no staining in the normal oral mucosa." (PMID 26555193, 2015). "Probing various publicly available datasets (GSE20347, GSE47404, GSE13937) to assess the expression of SOX4, EZH2 and HDAC3 in primary esophageal squamous and adenocarcinoma samples, we found SOX4 and EZH2 to be significantly upregulated in ESCC tumor samples (GSE20347), compared to normal tissues." (PMID 25644061, 2015). "SOX4, which belongs to the sex-determining region Y-related high-mobility group (SRY) box family, plays a critical role in embryonic development, cell fate decision, differentiation, and tumor development." (PMID 26578818, 2015). "This may lead to tumor progression and the metastasis of EAC and ESCC; SOX4, EZH2, HDAC3 and miR-31 emerge as potential therapeutic targets." (PMID 25644061, 2015). "Taken together, these findings suggest that SOX4 could mediate TGF-β-induced effects, such as EMT and maintenance of cancer stem cells in a variety of tumors, thereby contributing to tumor metastasis and progression." (PMID 23301048, 2013). "Quantification of SOX4 mRNA expression by quantitative real-time PCR in 10 tumor and non-tumor pairs of colon tissues." (PMID 23826209, 2013). "In HCC, SOX4 expression is greatly elevated in metastatic tumors compared to their non-metastatic counterparts, and shRNA-mediated SOX4 knockdown in metastatic HCC cells significantly reduced tumor metastasis." (PMID 23301048, 2013). "Indeed, SOX4 is directly regulated by hsa-miR-335 in cancer progression, while hsa-miR-125b coordinates STAT3 regulation in the proliferation of tumor cells." (PMID 23782521, 2013). "Paired t tests were used to analyze the differences in nuclear SOX4 expression between tumor and non-tumor tissues from each patient." (PMID 23285187, 2012). "Nuclear SOX4 expression was significantly higher in tumor tissues than in non-tumor tissues (P<0.001)." (PMID 23285187, 2012). "In the RT-PCR data, we noticed that SOX4 and TGFBI appear to be almost mutually exclusive in the tumor samples, suggesting a possibility that GBM may achieve activation of the non-canonical TGF-β through either SOX4 or TGFBI." (PMID 20419098, 2010).
tumor (continued). "Consistent with this, tumors 98-031, 7105 and 86-277 also had insertions near the Mef2c-cooperating gene Sox4, although only the insertion in tumor 7105 was clonal (data not shown)." (PMID 19461887, 2009). "Notably, this association was only observed in our MSS series, consistent with SOX4 being differentially expressed between MSS and MSI tumours." (PMID 19156145, 2009). "Certain target genes (e.g., ERBB4, SEMA4A, GCNT2 and SOX4) play critical roles in shaping two pathways related to the malignant fate of AT2 cells, which are inseparable from tumor differentiation and migration, suggesting that these genes may be novel therapeutic targets for further studies." (PMID 41415280, 2025). "In addition, we identified XRCC1 (AUC=0.847), SOX4 (AUC=0.985), and HOXD9 (AUC=0.767) as three molecules that could be ideal biomarkers to distinguish LGG from non-tumor tissues." (PMID 38217545, 2024). "Finally, in the sub-networks related to target lncRNAs, the expression levels of SOX4, SRM, and CPA4 (with the highest level of expression change based on bioinformatics analysis) mRNAs, in 32 tumor and 32 normal colorectal tissues, were investigated using qRT-PCR." (PMID 39028420, 2024). "To elucidate the expression of SOX4 in NSCLC, we initially compared the mRNA levels of SOX4 in LUSC and LUAD tissues and their adjacent normal tissues in the TCGA database and found that the expression of SOX4 in tumor tissues was significantly higher than that in adjacent normal tissues." (PMID 39349443, 2024). "However, in Smad4-negative cancer cells, KLF5 is not downregulated by TGF-β, and KLF5 and Sox4 cooperate to support tumor-initiating cells, thereby facilitating tumor progression." (PMID 38569937, 2024). "The present studies demonstrate that targeting eIF4A by zotatifin can robustly inhibit the translation of Sox4 and Fgfr1 in TNBC GEM models, resulting in not only the inhibition of cell proliferation, but also the induction of IFN-related pathways and remodeling of the tumor immune microenvironment." (PMID 37874652, 2023). "There is no information available for SOX4 in other tumor types." (PMID 37958409, 2023). "For example, miR-655 may suppress the proliferation of PCa cells and tumor metastasis by inhibiting TRIM24 and miR-30a may inhibit the androgen-independent growth of PCa cells by targeting the expression levels of MYBL2, FOXD1, and SOX4." (PMID 35782093, 2022). "The SOX4 level did not, however, vary between grade 1 and grade 2 tumours." (PMID 35522942, 2022). "To investigate whether CASC15 exerts tumor-promoting effects in NSCLC cells by influencing the expression of neighbouring genes, we firstly performed qPCR to analyze the expression levels of SOX4 and PRL upon CASC15 silencing." (PMID 33407675, 2021). "Furthermore, these findings may also suggest that additional oncogenic signaling pathways, downstream of TGFβ, may be activated by the SOX4/SMARCA4 complex and contribute to tumor development and progression." (PMID 33837205, 2021). "Since a majority of mice injected with SOX4KO organoids did not have a primary tumor we performed an alternative experiment to explore whether SOX4 also directly affects metastatic outgrowth." (PMID 34584219, 2021). "Thus, SOX4 would be a candidate for a universal oncogene that is independent of a tumor entity, and at the same time is expressed in non-cancer cells of embryonic origin." (PMID 29977599, 2018). "In addition, Stat3 or Sox4 depletion in TICs reduced the tumour initiation and TIC ratios, while Stat3 or Sox4 knockdown in non-TICs had little effect on tumour initiation." (PMID 27553854, 2016). "TGF-β-mediated induction of SOX4 and subsequent increased expression of N-cadherin could be sufficient to drive tumor metastasis even in the absence of a concomitant decrease in E-cadherin expression." (PMID 23301048, 2013).